STAT3 (signal transducer and activator of transcription 3)
Diseases named in the same sentence as STAT3 in open-access papers (continued):
Sharing a sentence is not in itself a finding about the gene and the disease.
tumor (continued). "Activation of STAT3 promotes tumor proliferation, angiogenesis, and metastasis, facilitates pro-tumor inflammation, and inhibits Th1 anti-tumor immune responses." (PMID 34367125, 2021). "Conventional T cells can differentiate into Tregs in response to IL-35-mediated STAT1/STAT3 signaling, yielding so-called iTr35 cells, which can mediate the relationship between IL-35 and tumor cells in TME, accelerating tumor cell growth and metastasis." (PMID 34093586, 2021). "They concluded with the result that indicated an effective treatment target with a combination of anti-IL-6R and STAT3 inhibitor as this was shown to reduce the tumour progression further." (PMID 34336101, 2021). "Further, IF and confocal analyses revealed significant reduction of cell proliferation marker Ki-67 as well as tumor angiogenesis marker CD31 in tumor tissues upon treatments with PS-acet.-STAT3 peptide." (PMID 33491667, 2021). "At the same time, the activation of NF-κB and STAT3 can increase the production of inflammatory factors, maintain the tumor inflammatory microenvironment, and form a vicious circle of “inflammation–tumor-inflammation”." (PMID 34079469, 2021). "Among others, inhibition of STAT3 was found to sensitize various types of tumor cells for radiation and chemotherapy." (PMID 34884773, 2021). "Consistently, activation of AhR/IL-6/STAT3/ NF-kB signaling was observed in TDO2 overexpression tumor tissues." (PMID 34657635, 2021). "Given the multifaceted role of STAT3 signaling in NSCLC tumor development and progression, this pathway represents a promising therapeutic target for anti-cancer therapy." (PMID 34944848, 2021). "Changes in tumor growth and immune phenotypes in response to molecules such as STAT3, KDM4A or heparanase already demonstrate unique responses that depend on their respective activities." (PMID 35069219, 2021). "Among these TFs, STAT3, and CEBP-β have been shown to associate with the hypoxic microenvironment, which is enriched with immunosuppressive tumour-associated macrophages." (PMID 35008787, 2021). "A series of experiments were performed to confirm that circUBE2Q2 regulates GC progression via the circUBE2Q2-miR-370-3p-STAT3 axis and promotes tumor metastasis through exosomal communication." (PMID 34611143, 2021). "While p-STAT3 has proved to be a difficult drug target, identifying molecules targeting p-STAT3 displayed great value in anti-tumor therapy." (PMID 33391405, 2021). "It has been reported that STAT3 inhibition induces tumor cell death and increases apoptosis of tumor cells by increasing the Bax/Bcl-2 ratio." (PMID 33807148, 2021). "In summary, our results show that the TME promotes tumour angiogenesis by activating STAT3 in vascular endothelial cells and that bufalin can precisely inhibit angiogenesis by targeting STAT3." (PMID 34496870, 2021). "STAT3 plays a significant role in tumor progression both in a tumor cell-intrinsic manner and through its ability to modulate the activity of the surrounding cell milieu." (PMID 34926570, 2021). "Tumor cell-derived LIF stimulates macrophages’ M2-type polarization through activating the STAT3 signaling pathway." (PMID 34604066, 2021). "IHC staining revealed that positive expressions of Ki-67, LIF and p-STAT3 in tumor sections of mice with knockdown of LBX2-AS1 were significantly lower than those of controls." (PMID 34729101, 2021). "Some studies showed that ROS-induced PD-L1 expression by regulating the JAK/STAT3 pathway, and ROS inducers also increased the level of PD-L1 expression in tumor cells." (PMID 34795841, 2021). "Tissue cytometry revealed high expression of STAT3 in virtually all of the alimentary tumour cells, as exemplified in a representative sample." (PMID 34680385, 2021).
tumor (continued). "The persistent STAT3 activation supports a protumorigenic microenvironment in PDAC by increasing the levels of immuno-suppressive cells, such as tumor-associated macrophages (TAM)." (PMID 33420372, 2021). "STAT3 signaling activation is magically converged in both tumor promotion and immunosuppression, such as the crosstalk between tumor cells and immune cells." (PMID 33957948, 2021). "In summary, our work unravels an IL-6-regulated cellular mechanism that controls Mφ-mediated tumor immunity through IL-10 and Stat3/HIF-1α/CD40 expression." (PMID 34103524, 2021). "Various signaling pathways are associated with chronic inflammation, including the MAPK, AKT, mTOR, STAT3, and/or NF-κB pathways, and can potentially lead to tumor promotion." (PMID 34950252, 2021). "Tumor-associated macrophages (TAMs) have also been demonstrated to increase tumor size, angiogenesis, intrahepatic metastasis, and the recurrence rate via the STAT3 signaling pathway in HCC cell lines." (PMID 34948424, 2021). "Once activated, STAT3 undergoes phosphorylation, homodimerization, nuclear translocation and DNA binding, subsequently driving the tumor proliferation, differentiation, apoptosis, cell transformation, invasion, angiogenesis, and immune evasion." (PMID 33957948, 2021). "Western blot analysis of tumor tissues was performed, and the expression of p-STAT3 and p-Akt was found to be significantly suppressed after Probio-M9 administration." (PMID 33808480, 2021). "STAT3 is a bona fide oncogene and has been observed to become active in many malignancies and through phosphorylation of on STAT3 (P-STAT3) to exert its tumor-promoting effects." (PMID 34445405, 2021). "And the IHC results showed GLA significantly inhibited cell proliferation and interfered STAT3 pathway on MM xenograft model tumor tissues." (PMID 34923957, 2021). "Constitutive activation of STAT3 has already been proven in tumor cells isolated from the patients with CTCL." (PMID 32270320, 2021). "Resveratrol had shown inhibitory activity on STAT3 acetylation, and it consequently reactivated several tumor suppressors’ genes, such as ESR1 in breast cancer and melanoma." (PMID 34942997, 2021). "Both pathways activate key transcription factors in tumor cells, primarily nuclear factor-kB, signal transducer and activator of transcription 3, and hypoxia-inducible factor 1a." (PMID 33591412, 2021). "In turn, Wu and colleagues (2014) confirmed the tumor growth inhibition after RSV intravesical treatment due to STAT3 signaling pathway inhibition (reduced expression of survivin, cyclin D1, c-Myc and VEGF)." (PMID 34360552, 2021). "Several lines of evidence demonstrate that the autocrine/paracrine IL‐6/JAK/STAT3 feed‐forward loop participates in tumor progression and shapes of the tumor microenvironment." (PMID 34375503, 2021). "\In addition to tumorigenesis, STAT3 and c-Myc play important roles in facilitating tumor cell glycolysis." (PMID 34608390, 2021). "To determine if STAT3 is also required for L1CAM-induced tumor initiation, we injected immunodeficient mice with Ov90-mock and Ov90-L1CAM cells and treated them with Napabucasin starting three days after injection." (PMID 34645505, 2021). "At the same time, IL-10 is an anti-inflammatory cytokine critical for dampening anti-tumor immune responses and upregulated by STAT3." (PMID 34956861, 2021). "For the validation of this analysis, the GEPIA expression level of the hub genes were also employed and gene- ITGAM, ITGAX, PTPRC along with STAT3 were found in lower expression levels in tumor cells." (PMID 33946372, 2021). "STAT3 plays an essential role in tumor development and has been considered as a promising target for cancer treatment, especially in NSCLC therapy." (PMID 34429133, 2021). "Previous studies report that HIF1 complex and IL-6/STAT3 signaling pathway plays a crucial role in tumor angiogenesis, and STAT3 Y705 phosphorylation modulates IL-6/STAT3 signal pathway activation." (PMID 34753906, 2021).
tumor (continued). "STAT3 activation has been reported to show positive correlation with the proliferation and metastasis of tumor, and STAT1 enhances innate and adaptive immunity, triggering in most instances anti-proliferative and pro-apoptotic responses in tumor cells." (PMID 33748122, 2021). "Strikingly, treatment of mice harboring H1650 NSCLC xenografts with the STAT3 inhibitor RITA in combination with doxorubicin significantly reduces tumor growth compared to monotherapy-treated groups." (PMID 34944848, 2021). "In athymic nude mice bearing NCI-H460 tumours, curcumin-induced inhibition of JAK and STAT3 phosphorylation led to reduced tumour weight and improved the survival rate of mice." (PMID 34834295, 2021). "It is known that the activation of STAT3 in many malignant tumors is related to tumor proliferation, invasion, metastasis, and resistance to chemotherapy and radiotherapy." (PMID 34521875, 2021). "In B-cell lymphoma cells, binding of the CD86 ligand to cytotoxic T-lymphocyte-associated antigen 4 (CTLA4) results in recruitment and phosphorylation of TYK2, which activates STAT3 to drive transcription of genes promoting tumor growth and survival." (PMID 34439323, 2021). "These tumor-promoting cytokines bind to their receptors, further stimulating STAT3 activation in adjacent CSCs." (PMID 34235155, 2021). "We confirmed that TGFβ1 acted on tumor cells, causing a series of changes: upregulation of LAMC1; phosphorylation of NF‐κB; secretion of CXCL1; phosphorylation of STAT3 in CAF; and finally, the induction of the formation of iCAF, that is, tumor‐promoting CAF." (PMID 34218518, 2021). "Secretory factors from S‐type cells promote survival and proliferation of neuroblastic tumour cells in a STAT3‐dependent manner." (PMID 33932101, 2021). "IL-6 produced in the TME activates the JAK/STAT3 signaling pathway, favoring tumor growth and metastasis." (PMID 34552929, 2021). "Meanwhile, tumor infiltrating immune cells secreted IL-6 is able to stimulate IL-6/STAT3 signaling pathway to promote the malignant behaviors of HCC cells." (PMID 34976809, 2021). "By analysing several protein markers altered by SD‐36, we detected significantly reduced levels of STAT3 and Mcl‐1 in the SD‐36‐treated U251 tumours." (PMID 34291563, 2021). "In the tumor-bearing host, STAT3 activation from tumor cells or from normal immune cells can both inhibit the secretion of inflammatory factors and reduce the immune surveillance of tumor cells." (PMID 34976809, 2021). "Some anticancer candidates such as fluorinated β-amino-ketone and AZD9159, antisense oligonucleotides, are used to inhibit the T regs, MDSC, and tumor growth via suppression of STAT3 expression and cascade." (PMID 34692527, 2021). "Some studies have indicated that STAT3 seems to inhibit autophagy in some types of tumours and infectious diseases, but others have shown that STAT3 activation can significantly enhance autophagy in some blood tumours and autoimmune and inflammatory diseases." (PMID 34645519, 2021). "The immunohistochemistry revealed that STAT3 and Ki‐67 expression was significantly higher in the MAP2K3‐KO group, while knockdown of STAT3 abolished this phenomenon, indicating that STAT3 knockdown diminished tumor activity induced by MAP2K3‐KO." (PMID 33660414, 2021). "In vivo investigations have indicated that RES suppresses tumor growth and stimulates apoptosis by inhibiting STAT3." (PMID 34488773, 2021). "While STAT3 activation in the TME is important in the first stages of tumor development, STAT3 activation in cancer cells is more associated with the metastatic process." (PMID 34440697, 2021). "Evidence of this is observed in tumor-bearing mice that have increased levels of phosphorylated STAT3 in MDSCs compared to immature myeloid cells from naive mice." (PMID 34065010, 2021). "In this study, we identified STAT3/CDK2/4/6 as an oncogenic prognosticator of cancer-associated fibroblasts and tumor immune infiltrations." (PMID 33668805, 2021).
tumor (continued). "Tumor cell-intrinsic STAT3 can also exert inhibitory effects on cytotoxic T-cell responses through the upregulation of immune checkpoint molecules such as PDL1." (PMID 34944848, 2021). "We measured the numbers of TANs and TAMs and the level of p-STAT3 expression using a TMA composed of primary tumor tissues from 359 patients with ICC." (PMID 33692217, 2021). "As one of many important regulatory factors in TME, STAT3 is a key target that connects the microenvironment with tumor cells." (PMID 33957948, 2021). "Additional evidence implies that autophagy is also responsible for tumour immune escape by stimulating signal transducer and activator of transcription 3 (STAT3) signalling, an oncogenic pathway." (PMID 33605033, 2021). "Activation of STAT3 is observed in TNBC tumors where epigenetic suppression of miR-146b leads to constitutive STAT3 activation and tumor growth." (PMID 34350123, 2021). "The activation and interaction of STAT3 and NF-κB play a key role in controlling the dialogue between tumor cells and their microenvironment, especially in inflammatory/tumor-infiltrating immune cells." (PMID 34079469, 2021). "Taken together, simultaneous targeting of STAT3 and the PI3K/mTOR pathway can sensitize PTEN-deficient cancer cells to BEZ235, and inhibit tumor growth in vivo." (PMID 33431808, 2021). "As a further confirmation of the effects of dual inhibition of Ref‐1 and STAT3 in PDAC tumours co‐implanted with CAFs, we performed an in vivo study using the stem cell/ STAT3 inhibitor Napa." (PMID 33274592, 2021). "In summary, we demonstrated that chronic inflammation in the tumor environment can stimulate the activity of the IL-6/STAT3 signaling, and STAT3 can directly inhibit the transcription of miR-520f-3p." (PMID 33500736, 2021). "Knock down of eIF2α or expression of activated STAT3 suppressed tumor cell killing reducing the lethality of the three-drug combination to that of GZ17-6.02 alone." (PMID 33898322, 2021). "STAT3 and p-STAT3 are often overexpressed in various human tumours and participate in cancer development and progression." (PMID 34789292, 2021). "Conversely, Hoelbl-Kovacic found that STAT3 knock-out in tumor cell lines can weaken the function of NK cells." (PMID 34759824, 2021). "For example, the inhibitors targeting the JAK1/STAT3 pathway play a role in both tumor cells and CAAs." (PMID 33413697, 2021). "Based on these evidences, our results pave the way to identify new genetic and epigenetic biomarkers that are useful to predict the therapeutic response of tumor patients to biologic drugs direct towards IL6/STAT3 axis." (PMID 34576335, 2021). "IL-6 activates STAT3, which has previously been shown to enhance tumor cell growth, resistance to chemotherapy, and tumor dissemination in some tumor types." (PMID 34209460, 2021). "Constitutive activation of STAT3 occurs in solid and haematologic tumours, but activation is transient in normal cells." (PMID 34291563, 2021). "Results from in vitro studies indicate that STAT3 inhibition increases the Bax/Bcl-2 ratio leading to apoptosis of tumor cells." (PMID 33807148, 2021). "All these data indicate thatmiR-650 promotes tumor cell motility by mediating SOCS3/JAK/STAT3 signalingactivation." (PMID 34450627, 2021). "In esophageal squamous cell carcinoma, tumor cells activate the STAT3 pathway on NK cells through IL6 and IL8, leading to down-regulation of NKp30 and NKG2D on NK cells and tumor progression." (PMID 34447383, 2021). "We observed a significant reduction in the DNA interaction ability of STAT3 in different tumor cells." (PMID 34771643, 2021). "To further identify the function of tumor‐derived exosomal STAT3 and p‐STAT3 in ADSCs, we cocultured ADSCs with these exosomes." (PMID 33999512, 2021).
tumor (continued). "The inhibition of S1PR1 expression down-regulates STAT3 function leading to halting in tumor cell survival and invasion." (PMID 33920887, 2021). "Tumor-derived IL-6/8 impairs the function of NK cells through STAT3 signaling and enhances malignancy in primary esophageal squamous cell carcinoma." (PMID 35011369, 2021). "IL-6 is a pro-tumorigenic cytokine that triggers JAK/STAT3 activation, which promotes tumor cell growth and suppresses tumor cell apoptosis." (PMID 33925400, 2021). "Accordingly, targeting the MET/STAT3 signaling pathway potentiates the anti-tumor efficacy of PI3K/AKT inhibitors in NSCLC tumor-bearing mice." (PMID 34944848, 2021). "Supporting the potent antitumor effects of PS-acet.-STAT3 peptide, we found massive cell death in tumor sections, as shown by the morphological features from H&E staining." (PMID 33491667, 2021). "The effects of the combination treatment on tumour volume are consistent with those from the Rux treated mice, confirming that overall, a combination STAT3 and Ref‐1 inhibitors reduced tumour growth in the presence of the appropriate microenvironment." (PMID 33274592, 2021). "As such, some studies demonstrated that the combination of anti-VEGF (Cediranib) and STAT3 inhibitors (AZD1480) for the treatment of glioblastoma in a mice model led to a decrease in the tumor volume and angiogenesis." (PMID 34440802, 2021). "STAT3 hyperactivation in tumor cells were generally induced by elevated IL-6 in the tumor microenvironment in the majority of human cancers." (PMID 34922636, 2021). "In colitis-associated cancer, S1P1 can interact directly with activated STAT3, enhancing tumor growth, metastasis, thus having a tumorigenic impact." (PMID 34943797, 2021). "AMPK/STAT3 signaling pathways are closely related to tumor biological functions, such as proliferation, and apoptosis." (PMID 34179090, 2021). "Through MDSCs secretion of INF-α and other mechanisms, STAT3 upregulates the expression of inhibitory immune checkpoints like PD-L1 on the surface of TAMs and tumor-infiltrating DCs." (PMID 34440802, 2021). "In A375 cells, curcumin promoted tumor cell apoptosis by inhibiting the JAK-2/STAT-3 signaling pathway and downregulating Bcl-2." (PMID 34680593, 2021). "It has been recognized that activation of p-STAT3 is a key factor in cells that constitute tumor stroma and lead to cancer pathogenesis." (PMID 33854974, 2021). "MiR-125a has been recognized as a tumor suppressor in many cancers; it is effective in malignancies pathogenesis such as breast cancer by affecting many transcription factors such as STAT3 and ERBB2." (PMID 33430952, 2021). "Mounting evidence shows that constitutively activated STAT3 contributes to tumour development and progression in most cancers, including breast, prostate, gastric, pancreas, colorectum, cervix, ovary, lung, melanoma and blood cancers." (PMID 33259114, 2021). "Our studies further provide proof of concept that a potentially novel STAT3 inhibitor specifically blocks STAT3 at K685, leading to potent antitumor effects in multiple tumor models." (PMID 33491667, 2021). "Tumor-derived CSF2 increases the expression of PD-L1 in granulocytes by activating the JAK/STAT3 signaling pathway, which inhibits the anti-tumor effect of T cells and contributes to the progression of gastric cancer and hepatocellular carcinoma." (PMID 34248982, 2021). "Subsequent studies are likely to confirm the roles of STAT3 and autophagy in tumor metastasis and chemoresistance and further investigate the synergistic impacts exerted by flubendazole with chemotherapies and targeted drugs." (PMID 34513827, 2021).